IL17A (interleukin 17A)
Diseases named in the same sentence as IL17A in open-access papers (continued):
Sharing a sentence is not in itself a finding about the gene and the disease.
infection (continued). "The production of adaptive cytokines by PBMCs, such as IFNγ and IL-17A, detected after 7 days of infection, was also compromised following the blockade of glycolysis." (PMID 32385235, 2020). "We and others have demonstrated a prominent role for IL-17A during infection with the lung-migrating nematode Nippostronglyus brasiliensis, a well-defined pulmonary model of type-2 immunity." (PMID 32636457, 2020). "IFNγ was neutralised at day −1 and 1 of infection in Il17a-KO and WT mice, and responses examined at d8pi, a time point when the type-2 response should be fully developed." (PMID 32636457, 2020). "Consistent with the results of this study, after 7 days of infection, the anti-IL-17A, anti-IL-22, and anti-IL-17A + anti-IL-22 groups showed more severe organ damage than the model group." (PMID 33178181, 2020). "To evaluate the impact of the infection in the pattern of cytokines in sera, we next performed ELISA tests of IL-4, IL-17A, IFN-γ, and TGF-β1 in patients and HC." (PMID 33281813, 2020). "Initial Th17 polarization was related to fungal load reduction at early stages of infection, as seen in the IL-17A neutralization assay, in which fungal cells are composed mostly of fragments of hyphae and conidia." (PMID 32542003, 2020). "We showed that, in addition to CCR6+ CD27– γδ T cells, the numbers of CCR6–CD27– γδ T cells increased along with their CXCR3 and IL‐17A expression during infection." (PMID 31777067, 2020). "Strikingly, IL-17A blockade during infection decreased IgG2a and IgA antibody levels as well as IFN-γ production, leading to an increase in mortality of vaccinated mice." (PMID 33193292, 2020). "While early IL-17A promotes the type-2 response, later in infection IL-17A acts to suppress and limit excessive type-2 immunity, particularly in ILC2s." (PMID 32636457, 2020). "IL-17A is a protective cytokine in some inflammatory diseases and in mycobacterial infections following an early infection." (PMID 32258066, 2020). "In response to the infection, IL17-A, induces a rapid proinflammatory cascade of chemokines and cytokines that facilitates the recruitment and activation of neutrophils and monocytes required for the early control of the pathogen by the immune system." (PMID 32193469, 2020). "IL-17A is a proinflammatory cytokine that plays essential roles in infections and inflammatory diseases." (PMID 33304351, 2020). "Nonetheless, a side-by-side comparison of the effects of anti-IL-17A or anti-TNF-α neutralizing antibodies in a murine infection model, confirmed the importance of TNF-α in the immune response against Mtb, in contrast to the IL-17 pathway." (PMID 32069329, 2020). "Mice pre-treated with IL-17A or IL-23 prior to infection with R. anatipestifer at a sub-lethal dose exhibited increased bacterial burden and spleen weight compared to untreated infected mice." (PMID 33175869, 2020). "In other pathologies such as Mycobacterium bovis Bacillus Calmette–Guérin infection, γδ T cells were identified as the main source of IL-17A in the peritoneal cavity during the early stages of infection." (PMID 32987705, 2020). "Various studies in mice have demonstrated the importance and pleiotropy of IL-17A in peritoneal inflammatory response during infection." (PMID 32987705, 2020). "The serum level of IL-17A in ABX mice was significantly decreased after infection, while IL-17A played a protective role in the resistance to C. albicans infection." (PMID 32460890, 2020). "Here, we show that asymptomatic infection with Plasmodium is associated with higher levels of IFN-γ and IL-17A." (PMID 33281757, 2020). "The levels of IL-17A were significantly increased beginning at 11 dpi in the low-dose, middle-dose, and high-dose infection groups, which peaked at 17 dpi, 30 dpi, and 30 dpi, respectively." (PMID 32085808, 2020).
infection (continued). "These IL-17A levels, however, were much lower when compared to IN-vaccination (mean 127 vs 2489 pg/mL, before infection; mean 422 vs 4782 pg/mL, after infection; 1:1 stimuli)." (PMID 32040500, 2020). "When mice were treated with anti-CD20 mAb prior to infection, significant decreases in the levels of IL-6- and IL-17A-producing lymphoid cells were observed." (PMID 32398312, 2020). "While expression of IL-17A and IL-1β was highest early after infection, expression of IL-23 was elevated in the late stage of HN878 infection when differences in susceptibility between the sexes became apparent." (PMID 32198367, 2020). "While WT mice showed a significant increase in absolute numbers and frequency of GATA3+CD4+ T cells upon infection, Il17a-KO mice had a significantly lower frequency of GATA3+CD4+ T cells and failed to upregulate these cells on d7pi compared with WT controls." (PMID 32636457, 2020). "It is well known that IL-22 producing CD4+ T cells are essential for controlling Cr infection; however, the T cell-derived cytokines (IL17A, IFN-γ and TNF-α) contribute to intestinal tissue injury either directly or indirectly." (PMID 33076301, 2020). "Similar to infection with N. brasiliensis, we also observed an upregulation of IFNγ in the lung during T. muris infection in Il17a-KO mice." (PMID 32636457, 2020). "Upon infection with C. albicans, dermal γδ T cells produce IL-17A to provide resistance to cutaneous candidiasis, and this requires IL-23 production by dermal DCs." (PMID 32887412, 2020). "Intranasal (IN) vaccinations using dmLT have been shown to elicit IL-17A responses and this is proposed to be important for eliciting immunological protection against the establishment of Pa infection." (PMID 33281815, 2020). "IL-17A plays a particularly important role in host defense against infection with pathogens such as Staphylococcus aureus and Citrobacter rodentium, Chlamydia muridarum, and R. anatipestifer." (PMID 33175869, 2020). "Our observations show that during infection, the increase in Vγ2 cells was accompanied by an increase in their secreted IL-17A." (PMID 32611373, 2020). "An analysis of cytokines associated with T cell function revealed that patients who developed fatal S. aureus infections had lower expression of IL-2 and IL-17A than those who survived the infection." (PMID 33291260, 2020). "Mice infected with Cr had increased expression of multiple cytokines including IL-17A, IL-22, IL-6, and IL-1β mRNA in colonic tissue 12 days after infection." (PMID 32230738, 2020). "Likely, IL-17A-mediated response is correlated with disease severity following infections by Epstein-Barr virus (EBV), herpes simplex virus (HSV), respiratory syncytial virus (RSV), vaccinia virus, and hepatitis virus." (PMID 32849528, 2020). "Ingenuity pathway analyses also suggested the pro-inflammatory cytokine IL-17A to regulate the vaginal host defences during infection." (PMID 32439855, 2020). "IL-17A regulation of type-2 immunity was lung-specific and infection with Trichuris muris revealed that IL-17A promotes a type-2 immune response in the lung even when infection is restricted to the intestine." (PMID 32636457, 2020). "At 30 hours after infection, IL-17A was detected at a mean level of 450.59 pg/mL in the loops inoculated with the C. jejuni wild-type strain compared to 252.3 pg/mL in the control loops." (PMID 32887530, 2020). "After the infection with T. cruzi, interleukin-17A (IL-17A) is produced by T helper 17 (Th17) cells, subset of CD4+ T cells, and innate lymphoid cells." (PMID 32193469, 2020). "First, the sustained IL-17A production during the clinical phases of primary infections is quite surprising." (PMID 33322218, 2020). "IL-17A responses are required for controlling infection with fungal pathogens, including Aspergillus fumigatus, Pneumocystis carinii, Cryptococcus neoformans, and Candida albicans." (PMID 32849528, 2020).
infection (continued). "To help better understand IL-23's importance on the prevalence of IL-17A as previously reported in, we looked into the plasma IL-23 levels as it corresponds to the infection status." (PMID 32258066, 2020). "The same pattern of IL-17A expression is found in plasma from cows with JD ELISA scores correlating to progressing stages of infection." (PMID 32258066, 2020). "Compared with adult mice, a significant decrease in γδ T cell-mediated IL-17A responses was noted in RSV-infected neonatal mice during initial infection." (PMID 33183352, 2020). "Duration of shedding was inversely correlated with plasma levels of T‐cell cytokines IL‐1β and IL‐17A at the initial phase of infection, and patients had lower levels of pro‐inflammatory cytokines during intermittent shedding." (PMID 32742654, 2020). "Here, TGF-β, and not IL-13, was decreased in the KO mouse livers at 6 weeks post-infection; IL-17A was also decreased in the KO mouse livers." (PMID 32611373, 2020). "In the early stages of the infection, the IL-17A is a crucial cytokine secreted by a wide range cell types such as Th17, B cells, innate lymphoid cells, CD4+, CD8+, gamma-delta T and invariant NKT10-13,32." (PMID 32193469, 2020). "IFN‐γ and IL‐17A play an important role in the host defense against pathogens and are known to be expressed by γδ T cells early during infection." (PMID 31777067, 2020). "IL-17A signaling also has a protective role to the host during infection of adenovirus by inducing high levels of IL-7R and RORγt expression in mouse liver cells." (PMID 33304351, 2020). "Our data demonstrate an impairment of the type-2 immune response in the lung during infection of Il17a-KO mice with the lung-migrating nematode N. brasiliensis." (PMID 32636457, 2020). "IL-17A plays an important role in the recruitment of neutrophils and other immune cells to the infection sites." (PMID 32680482, 2020). "This is supported by the reduced airway tissue damage and burden of infection in an Il17a−/− model of PA infection." (PMID 31089134, 2019). "In sera collected at 24 h after this infection, duIL-23p19 expression levels were unchanged, whereas IL-17A significantly upregulated." (PMID 31519917, 2019). "Continues IL-17A expression, will result in a continues influx of neutrophils at the site of infection and a continuous influx of tissue damage and remodeling due to the production of ROS and metalloproteases." (PMID 31295246, 2019). "It has been reported that IL-17A is protective during primary infection of virulent Mtb, and IL-17A is predominantly produced by γδ T cells in the lungs early after Mtb infection." (PMID 32038633, 2019). "While IL-17A expression extended throughout the length of Muller cells following infection with the RHΔROP16 and PRU parental strains, expression in the RH and PRU ROP16-I infected mice seemed to be restricted to the endfeet region of Muller cells." (PMID 30901349, 2019). "For example, IL17A is produced by CD4+ T lymphocytes in order to eliminate the primary infection, and to establish an effective memory response." (PMID 31616423, 2019). "aureus coinfected mice with neutralizing anti-IL-17A or anti-IL-1β antibodies through the first two weeks infection." (PMID 31107882, 2019). "Other cytokines that were slightly elevated at day 2 of infection were Th17-dependent IL-17A, Th1-dependent gamma interferon (IFN-γ), and IL-5." (PMID 31548315, 2019). "In contrast, our previous studies demonstrated the detrimental role of Th17 cytokines, characterized by the production of IL-17A, in OT, at least in infection with type II strains." (PMID 30901349, 2019). "Mice treated with IL-17A prior to i.p. infection with MCMV exhibited significantly greater viral burden in spleen and lungs 5 days postinfection (dpi) compared to control animals treated with vehicle control." (PMID 31239384, 2019). "IL-17A, with altered gene expression in both murine and human infections, was more highly expressed in both our infection models." (PMID 31329596, 2019).
infection (continued). "More IL-17A will also be produced to attract even more neutrophils to the site of infection, which results in even a higher production of ROS." (PMID 31295246, 2019). "In accordance with our study, ex vivo infection reduced IL-17A levels in lung slices of asthmatic animals." (PMID 31640701, 2019). "At 12 h after the infection, interferon-gamma, interleukin-10, interleukin-17A, interleukin-1 beta, interleukin-6, and tumor necrosis factor alpha (TNF-α) tended to be suppressed with micafungin treatment in both PF and control mouse models." (PMID 31249356, 2019). "However, IL-17 (including increased expressions of Il17a, Il1a and Il22) and granulocyte-associated (L10 and L11) responses were most pronounced during B. pseudomallei infection, with this infection also exhibiting increased IFN gene signatures (L5 and L7) in contrast to the C. albicans infection." (PMID 31253760, 2019). "IL-17A stimulation resulted in marked down-regulation of IL-13 at all-time points post-infection when compared to untreated controls." (PMID 31681209, 2019). "We found that SWAP stimulated significant secretion of IL-17A by splenocytes at 6 and 8 weeks post infection, with the 6 week splenocytes producing more IL-17A than the 8 week cells." (PMID 30653492, 2019). "Whereas, primary infection with S. flexneri induces differentiation of CD4+ cells to Th17 cells that produce IL-17A and IL-22, secondary infection also produces Th1 cells that secrete IFN-γ." (PMID 30800131, 2019). "Through the combined effects of IL-6 and TGF-β, CD4+ T cells differentiate into Th17 cells and secrete IL-17A, which plays a key role in host defense against infection." (PMID 31297140, 2019). "Next, we investigated IL-17A and IL-23p19 expression in the sera of ducks at 24 h post-infection with R. anatipestifer." (PMID 31519917, 2019). "Expression of IL-2, important for inducing the Th1 response, was decreased significantly, the levels of TGF-β and IL-17A increased significantly at 30 h after infection." (PMID 31855175, 2019). "ETBF infection is characterized by induction of the pro-inflammatory IL-17A cytokine in colon of C57BL/6 mice." (PMID 31540059, 2019). "In the immunocompetent mice, the Chr6ABB strain induced significantly less CCL3, CXCL1 (KC), IL-1β, IL-17A, and the p19 subunit of IL-23 in the oral tissues relative to the progenitor strain after 1 day of infection." (PMID 31091232, 2019). "IL-17A and IL-17F reduced the number of intracellular bacteria in an ex vivo model of infection using pediatric intestinal biopsies suggesting their importance in intestinal immunity." (PMID 31427597, 2019). "In vitro infection experiments revealed decreased Th17 and Tc17 cell frequency and IL-17A levels at various time points postinfection." (PMID 31061831, 2019). "Compared to the anti-IL-12/23 agent, anti-IL-17A agents are generally considered to be safer in regard to latent TB reactivation or infection." (PMID 31881026, 2019). "The exacerbated lesion size corresponded to an IL-17A response, which developed from an innate response of skin γδ and non-γδ T cells during the first week of infection, into an adaptive response of L. major antigen-responsive Th17 cells at later time points." (PMID 31107882, 2019). "Dam 2 had an increase in IL-1β, IL-2, IL-6, IL-7, IL-12, IL-15, IL-16 and IL-17A, peaking on day 14 post-infection for all but IL-12 and IL-15 which peaked on day 7 post-infection." (PMID 30657788, 2019). "Still, proinflammatory cytokines IFNγ and IL-17A were dominant, depicting an effort of host defense to overcome infection." (PMID 31318916, 2019). "Cytokines IL-6 and IL-17A, in particular, are important for coordinating neutrophil trafficking to areas of infection." (PMID 31206562, 2019). "We extended our analysis beyond the conventional IFNγ response by measuring TNFα, IL2, and IL17a producing T-cells as well, both in the periphery as well as at the site of the infection at various time points after infection." (PMID 31736945, 2019).
infection (continued). "Comparison between the control and the infected pups showed a significant increase of IL-17A levels at day 60 post infection (i.e. 64 days old), whereas Mbl2 was significantly upregulated at days 21 and 60 post infection (i.e. 25 and 64 days old respectively)." (PMID 31222079, 2019). "Immunized mice also induced higher levels of CD4+ IL-17A+ T cells by our final time point of 22 weeks post infection, similar to findings in human clinical studies." (PMID 29795025, 2018). "The rapid induction of IL-17A and IL-17F within 24 hours post-infection in experimentally infected mice suggested that innate cells also participate in cytokine production in the infected mucosa." (PMID 29782555, 2018). "After identification of multiple and partially overlapping myeloid cell subsets producing IL-17A-inducing cytokines, we aimed at evaluating their functional relevance for IL-17A production during infection." (PMID 29782555, 2018). "By contrast, for the groups intraperitoneally inoculated with F. pedrosoi-hyphae or sclerotic cells, an inhibited IL-17A production in the spleen can be only detected in the latter phase of infection." (PMID 29481557, 2018). "The concentration of IL-12/23 was elevated at days 1 and 3 after A. fumigatus infection, whereas the concentration of IL-17A was only found to be elevated at day 3 after infection." (PMID 30687649, 2018). "Because Il17a and Il17f transcript levels are maximal on day 1 post-infection with C. albicans strain SC5314, we focused our analysis on this time point." (PMID 29782555, 2018). "To begin addressing the potential contributions of lymphocytes to the host defense upon infection with the fbp1Δ mutant, we treated IL-17A−/− mice with neutralizing antibodies to IFN-γ to target the main effector cytokines of Th1 and Th17 cells." (PMID 29317510, 2018). "Using IL17A neutralized antibody experiment also supported that IL17A was important to promote IL12 produced by DC in Cm infection." (PMID 29743811, 2018). "It is worth mentioning that γδ T cell is the highest producer of IL-17A but the protection conferred by IL-17A is mainly mediated by Th17 cells following Cm infection." (PMID 29670466, 2018). "The role of microbiome, and SCFA in particular, on epithelial cells and APC in maintaining or inducing these Tregs, as well as in IL-17A induction in cells other than Th17 cells during infection will be investigated in the future." (PMID 30197637, 2018). "Concentrations of TNF-α, IFN-γ, IL-17A, and IL-22 rose sharply in the milk of UI goats when infection was out of control." (PMID 30045763, 2018). "IL-17A and IL-17F induce neutrophil recruitment from the bloodstream to the site of infection where these cells aid to prevent Candida dissemination." (PMID 29371502, 2018). "The increase in immune cytokines (IL-12p70, IL-4, IL-5, and IL-17A) induced by SPY1 were further upregulated by P17 treatment, whereas the decrease in the infection-associated inflammatory cytokine TNF-α by SPY1 was reversed." (PMID 30116243, 2018). "We set out to characterize cells with the potential to produce IL-17A and IL-17F in response to C. albicans at the site of infection." (PMID 29782555, 2018). "Quantification of the CD90+ and CD90+IL-17A+ subpopulations revealed an expansion of all subsets within the first 24 hours of infection." (PMID 29782555, 2018). "Further, role of IL-17A has been explored to impart protection by chemokine-mediated recruitment of Th1 cells at the site of infection." (PMID 30305097, 2018). "To confirm that γδ T cells were a significant source of IL-17A during infection, we administered an antibody that depletes γδ T cells 6 hours before infection." (PMID 29813133, 2018). "Our previous studies have shown that γδ T cells are the major producer of IL-17A in the very early stages of infection and depletion of γδ T cells by administration of mAb (GL3) against TCRγδ i.n. exists more body weight loss following Cm lung infection." (PMID 29670466, 2018).